EGFR (epidermal growth factor receptor)
Diseases named in the same sentence as EGFR in open-access papers (continued):
Sharing a sentence is not in itself a finding about the gene and the disease.
adenocarcinoma (continued). "The first study, retrospective, was conducted on a sample consisting of 131 patients with advanced (stages IIIB and IV) EGFR-mutant adenocarcinoma who had not received prior treatment." (PMID 40786517, 2025). "It correlates with size and staging, indicating a poor prognosis, whereas in adenocarcinomas, it indicates the paucity of treatment response with or without epidermal growth factor receptor (EGFR) in advanced stages." (PMID 40558585, 2025). "Studies have shown that EGFR mutations in NSCLC are more common in women, light or non-smokers, patients with adenocarcinoma histology, and Asian populations." (PMID 40862783, 2025). "Similar to EGFR mutations, Anaplastic Lymphoma Kinase (ALK) (typically translocations) typically occurs in non-smoker NSCLC patients with adenocarcinoma histotype in approximately 3–5% of NSCLC cases." (PMID 40243903, 2025). "Of the 886 patients included, most were female (67.2%, n = 499/743), non-smokers (73.8%; n = 498/675), had adenocarcinoma (97.9%; n = 571/583), and received EGFR-TKI rechallenge as a third-line therapy (82.9%; n = 561/677)." (PMID 39064005, 2024). "In the case of adenocarcinoma, potential targets include KRAS, EGFR, ALK, ERBB2, and/or BRAF." (PMID 38994972, 2024). "EGFR mutations were more frequently observed in women, non-smokers, early TNM stage, and were associated with a higher frequency of adenocarcinoma." (PMID 38783331, 2024). "Case studies have reported benefit of BRAF/MEK inhibition in BRAF mutated colorectal NEC, and a BRAF/EGFR-inhibitor combination is approved for BRAF mutated CRC, not limited to adenocarcinomas." (PMID 38909137, 2024). "An earlier report categorized ‘good prognosis’ and ‘bad prognosis’ groups separately for adenocarcinoma and squamous carcinoma based on expression patterns of sets of six proteins (c-SRC, CCNE1, TTF1, P65, CHK1, and JNK1/MPK1) and five proteins (EGFR, SOX2, CDH1, AKT1, and MAPK14), respectively." (PMID 39513892, 2024). "It is well known that EGFR mutations in NSCLC frequently occur in East Asians, females, non-smokers and adenocarcinomas." (PMID 36149029, 2023). "Meanwhile, UFT users frequently were never smokers, adenocarcinoma, pathologic stage IB disease, mutant EGFR, and at medical center for treatment." (PMID 37559409, 2023). "This patient has diagnosed with stage IIIB adenocarcinoma without ALK translocation and EGFR mutation in the left lower lobe, thus three cycles of neoadjuvant Toripalimab combined with chemotherapy were used for the surgical opportunity." (PMID 37256186, 2023). "We excluded from the MVA the co-variables that correlated significantly with EGFR: never-smoking (p < 0.0001), adenocarcinoma histology (p = 0.013), and the time interval between radiation and surgery (p = 0.048)." (PMID 37751214, 2023). "Previous studies have shown that similar to other EGFR variants, EGFR/ERBB2 ex20 ins/dup is predominantly found in adenocarcinoma, non-smokers, and women." (PMID 37284196, 2023). "Evaluation was limited to patients with non-metastatic patients with adenocarcinoma, a disease driven by perturbed EGFR-pathways signaling." (PMID 37399454, 2023). "Activating mutations of the epidermal growth factor receptor (EGFR) gene are detected in 15–20% of patients with non-small-cell lung cancer (NSCLC), predominantly in patients with adenocarcinomas, without a smoking history, in women, and Asian patients." (PMID 36765799, 2023).
adenocarcinoma (continued). "Although gene mutations in patients’ lesions have been detected, it was reported that the clinical features of adenocarcinoma in female non-smokers positively correlated with the effects of EGFR-TKI drugs." (PMID 35029237, 2022). "Case #1 had an EGFR L858R mutant adenocarcinoma that was initially negative for ALK expression by immunohistochemistry (IHC)." (PMID 36153311, 2022). "The patient we reported was one with 2 driver genes for EGFR; however, it was reported that some clinical features such as Asian, woman, non-smoker, and adenocarcinoma positively correlated with the efficacy of EGFR-TKI drugs." (PMID 35029237, 2022). "In subgroup analysis, the median OS in patients with adenocarcinoma with EGFR/ALK wild type has not yet been reached." (PMID 35372004, 2022). "Epidermal growth factor receptor (EGFR) mutations are found in 15–50% of non-small cell lung cancers (NSCLC), especially in women, non-smokers, Asians, and patients with adenocarcinoma." (PMID 36085020, 2022). "Hence, 213 patients (21.3%) and 188 patients (18.8%) were categorized as EGFR/ALK-wild type adenocarcinoma and non-adenocarcinoma groups, respectively." (PMID 35980949, 2022). "Epidermal growth factor receptor (EGFR) mutations in the tyrosine kinase domain are common in NSCLC patients, with higher rates particularly in those with adenocarcinoma, non-smokers, females, and Asian populations." (PMID 36429891, 2022). "All patients were untreated before enrollment and had histologically confirmed adenocarcinoma without sensitizing EGFR/ALK/ROS1 alterations." (PMID 34724131, 2022). "The patient subsequently underwent CT-guided percutaneous lung biopsy of pulmonary lesion, which revealed adenocarcinoma with EGFR exon 19 deletion without EGFR T790M and other resistant mutations." (PMID 35747829, 2022). "Adenocarcinoma (ADC), never-smoker status, and negative CA 125 and SCC results were predictors of EGFR mutations, while younger age and never-smoker status were independent predictors of ALK rearrangement." (PMID 35624472, 2022). "Because EGFR TKI, especially erlotinib (Tarceva) is indicated for the second‐line treatment or beyond after the failure of previous chemotherapy for NSCLC (not limited to adenocarcinoma)." (PMID 36214468, 2022). "EGFR- and ALK mutations are mainly found in patients with adenocarcinoma, and in Norway all patients with non-squamous NSCLC are routinely tested for these mutations." (PMID 36523970, 2022). "This implied that as long as the patients harbored EGFR driver mutations, regardless of lung SCC or adenocarcinoma, the outcome for the mutation number was similar." (PMID 34195081, 2021). "Like EGFR mutations, the frequency of HER2 mutations is significantly increased in non-smokers, women, persons of Asian descent, and adenocarcinoma NSCLCs." (PMID 39035769, 2021). "This suggests that although with EGFR mutation, the effect of SCC patients on TKI is not as good as that of adenocarcinoma patients, but the effect of female patients with SCC is better than that of male patients." (PMID 33869057, 2021). "Despite the high incidence of bone metastases in EGFR+ adenocarcinoma, there is a lack of screening for, and reporting on bone metastases in clinical trials, as well as permitted bone-targeted agents and SREs." (PMID 34201833, 2021). "A tendency of longer median PFS was observed in patients with adenocarcinoma, EGFR wild type, stage IV, no liver metastasis, former smoker, ≥2 previous treatment lines, no previous VEGF or EGFR target therapies in anlotinib plus immunotherapy group." (PMID 34395243, 2021). "Patients with EGFR 19delins were mostly women (24/41), non-smokers (34/41), stage IV disease (41/41) and adenocarcinoma histology (40/41)." (PMID 34774017, 2021).
adenocarcinoma (continued). "Based on those promising results, EGFR-TKIs have been recently recommended as the first-line therapy for never-smokers with adenocarcinoma of the lung having asymptomatic synchronous BM." (PMID 33531991, 2021). "While molecularly targeted therapy has revolutionized the treatment of adenocarcinoma with genetic alterations, including the epidermal growth factor receptor (EGFR) and anaplastic lymphoma kinase, treatment options for SCC are relatively limited compared to those of adenocarcinoma." (PMID 33586312, 2021). "When DM patients were further categorized into three tertiles according to the HbA1c level (low: 4.5-5.7, middle: 5.8-6.1, high: 6.2-10.7), those in the high tertile tended to be elder, male, ever smoker, non-adenocarcinoma, with greater BMI, CVD and wildtype EGFR." (PMID 34868942, 2021). "We did not identify significantly higher TMB in our EGFR-mutant SCC patients compared to those with adenocarcinoma, consistent with previous reports." (PMID 34195081, 2021). "For example, in our cohort, canonical oncodriver mutations were identified in three of the six tumors with an adenocarcinoma component (SOS1 in Pa34, EGFR/PIK3CA in Pa35, and KRAS/PIK3CA in Pa37) compared to pure LUADs, the majority of which harbor driver mutations." (PMID 34873156, 2021). "EGFR/ALK-negative/unknown patients, especially for those with adenocarcinoma, can significantly benefit from chemotherapy consisting of pemetrexed plus platinum." (PMID 33163410, 2020). "Our case was confirmed as stage I for adenocarcinoma (T1aN0M0), and thus the EGFR-TKI was not indicated." (PMID 32727606, 2020). "Of the adenocarcinoma patients tested, 6/6 were negative for EGFR (epidermal growth factor receptor) mutation, 2/3 were ALK (Anaplastic lymphoma kinase gene) positive, and 1/5 were KRAS (Kristen rat sarcoma viral oncogene) mutant." (PMID 32754271, 2020). "The hypothesis that EGFR-TKI treatment can affect CEA expression was based on the case of a 55-year-old male, who was initially diagnosed with clinical stage IV adenocarcinoma." (PMID 32034239, 2020). "In a head-to-head comparison of responders vs. non-responders, patients with advanced adenocarcinoma of the lung on gefitinib, an EGFR tyrosine kinase inhibitor, showed significant decrease in tracer uptake seven days after the start of therapy." (PMID 31935818, 2020). "We found that EGFR positive advanced adenocarcinoma patients had better OS compared with EGFR negative due to response to TKI treatment." (PMID 32053675, 2020). "Epidermal growth factor receptor (EGFR) gene mutations are related to some specific characteristics, such as no smoking histology, female gender, adenocarcinoma, and Asian populations." (PMID 30956990, 2019). "Our results did not indicate that TTF-1 was a predictive marker for treatment outcomes following first-line pemetrexed-based therapy among patients with EGFR-negative adenocarcinoma." (PMID 31196060, 2019). "The authors confirmed that there was a significantly increased risk of presenting EGFR mutations and ALK-EML4 fusions in never smokers compared to ever smokers with adenocarcinoma." (PMID 31711449, 2019). "Targeted therapy including anti-angiogenesis agents and epidermal growth factor receptor inhibitors obtains authorization for the treatment of adenocarcinoma, but not SCC." (PMID 31920637, 2019). "In contrast, a subset of LAD patients remain without EGFR, KRAS, and ALK mutations (triple-negative (TN) adenocarcinomas)." (PMID 31093306, 2019). "The prognostic significance of TTF-1 among patients with wild-type EGFR adenocarcinoma has not been studied adequately." (PMID 31196060, 2019).
adenocarcinoma (continued). "Adenocarcinoma with exon 21 mutation showed a significantly higher GGO volume percentage than in tumors with exon 19 mutation and those without EGFR mutation." (PMID 30956990, 2019). "p65BTK was significantly over-expressed in EGFR-wild type (wt) adenocarcinomas (AdC) from non-smoker patients and its expression was also preserved at the metastatic site." (PMID 31200752, 2019). "Testing for these gene mutations will ultimately determine the appropriate treatment to go forward with when treating adenocarcinoma; hence, if the K-RAS mutation is present, that would indicate that the anti-EGFR treatment will not work." (PMID 30956908, 2019). "This limitation is significant in studies of NSCLC since actionable (responsive to tyrosine kinase inhibitors) exon 19 deletions in the EGFR oncogene are common in non-smoker NSCLC patients (mainly of the adenocarcinoma subtype)." (PMID 29301485, 2018). "Because of the interaction between EGFR and integrin β4, inhibition of a single target is not sufficient to block proliferation and growth of human adenocarcinoma cells of the stomach." (PMID 29618949, 2018). "EGFR and HER2 protein expression levels were evaluated in 183 intestinal-type adenocarcinomas." (PMID 29046940, 2018). "Patients with EGFR double mutations were more likely to be nonsmokers, have an Eastern Cooperative Oncology Group Performance Status (ECOG PS) of 0-1, have adenocarcinoma, and be at stage III-IV." (PMID 29581983, 2018). "Histopathological analysis of the retrieved specimen later revealed an epidermal growth factor receptor (EGFR) negative adenocarcinoma." (PMID 29362884, 2018). "As of now, anti-EGFR agents should not be used in the first-line treatment of adenocarcinoma of the upper gastrointestinal tract." (PMID 29228748, 2017). "The HR for 1‐year OS for erlotinib recipients was 1.10 (1.03–1.18) in the whole cohort, 1.08 (0.98–1.18) in the EGFR‐TKI responders, 1.08 (1.02–1.16) in the adherent subgroup, 1.89 (1.62–2.09) in the adenocarcinoma subgroup, and 1.87 (1.47–2.37) in the adenocarcinoma with second‐line TKIs subgroup." (PMID 28639751, 2017). "Moreover, the benefit was observed in four subpopulations: EGFR‐TKI responders, adherent patients, adenocarcinoma patients, and adenocarcinoma patients receiving TKIs as second‐line therapy." (PMID 28639751, 2017). "In conclusion, in the absence of known EGFR mutational status, intercalating and maintenance use of gefitinib improves the PFS and OS of NSCLC patients of the adenocarcinoma subtype, or never or former light smokers who have achieved SD with chemotherapy." (PMID 28814805, 2017). "The HR for 1‐year PFS for receiving erlotinib was 1.15 (1.09–1.21) in the whole cohort, 1.11 (1.03–1.17) in the EGFR‐TKI responders, 1.16 (1.08–1.25) in the adherent subgroup, 1.35 (1.24–1.47) in the adenocarcinoma subgroup, and 1.39 (1.22–1.59) in the adenocarcinoma with second‐line TKIs subgroup." (PMID 28639751, 2017). "These patients may benefit from EGFR TKIs and BRAF inhibitors like other NSCLCs, especially adenocarcinomas." (PMID 28638113, 2017). "In the MWA plus EGFR-TKIs group, 26 were women, 13 were aged 65 years or older, 33 had adenocarcinoma histology and an ECOG PS of 1, and 28 were nonsmokers." (PMID 28915624, 2017). "EGFR common mutations in NSCLC patients with BM were significantly associated with never-smoking, female gender and histology of adenocarcinoma (P = 0.000, P = 0.000, P = 0.000; respectively)." (PMID 28211502, 2017). "However, SCLC can also revert to adenocarcinoma after chemotherapy for SCLC and regain sensitivity to EGFR-TKI." (PMID 29312580, 2017). "In the EGFR-TKIs group, 13 were women aged 65 years or older, 23 had adenocarcinoma histology, 21 had an ECOG PS of 1, and 17 were nonsmokers." (PMID 28915624, 2017). "As of now, anti-EGFR antibodies should not be used in the treatment of adenocarcinoma of the upper gastrointestinal tract." (PMID 29228748, 2017).
adenocarcinoma (continued). "EGFR testing tended to be more likely among patients with stage IV disease (all histologies: 19.9%; adenocarcinomas: 22.6%) but variations across stage did not tend to be statistically significant." (PMID 27294665, 2016). "The negative correlation between MIIP and EGFR protein expression observed in vitro was verified in adenocarcinoma NSCLC specimens." (PMID 26824318, 2016). "EGFR TKIs were found to be preferentially active in patients with adenocarcinomas, never-smokers, and patients of Southeast Asian ethnicity." (PMID 26970967, 2016). "In tissue samples from the primary site, we typically find that the newly diagnosed adenocarcinoma is EGFR positive; however, we do not know if the metastatic sites are also EGFR positive." (PMID 28293661, 2016). "Younger patients are more likely to be female, never-smokers, adenocarcinoma, and harbor wild type EGFR gene." (PMID 27191886, 2016). "In our institute we recently diagnosed a patient with adenocarcinoma (a 50-year-old woman, non-smoker, and EGFR positive) and we administered afatinib." (PMID 28293661, 2016). "Mutations in EGFR occur in approximately 15% of white and African American patients with NSCLC; 30% of NSCLC of Asian ethnicity; and are associated with adenocarcinoma histology, female gender, and nonsmoking status." (PMID 29282427, 2016). "In addition, a previous study reported that the patients who expressed sensitive mutations in non-adenocarcinoma responded poorly and non-effectively to the EGFR-TKIs, and hence whether it is even a necessity to undergo a routine mutation test in the absence of adenocarcinomas." (PMID 27992557, 2016). "Epidermal growth factor receptor (EGFR) mutations occur more frequently in non-small cell lung cancer (NSCLC) of women, never smokers, Asian population and those with adenocarcinoma." (PMID 26302346, 2015). "These histologic changes (from adenosquamous to pure squamous to pure adenocarcinoma) have been described but not before in the absence of any selection pressure with EGFR tyrosine kinase inhibitors." (PMID 26366316, 2015). "Similar to EGFR mutations, ALK rearrangements are associated with distinct clinical features, including younger age at diagnosis, never of light smokers and adenocarcinoma histology." (PMID 25789627, 2015). "The second case report demonstrated repeated responses to EGFR TKIs in a woman with adenocarcinoma and no history of smoking." (PMID 25699082, 2015). "By contrast, patients with PD-L1 positive tumors were more likely to be female and/or never or former smokers with EGFR-mutant or ALK-translocated adenocarcinoma histology." (PMID 26175921, 2015). "Non-smoking patients with adenocarcinoma and patients with mutant EGFR, who were expected to benefit from gefitinib alone, were excluded from the analysis." (PMID 26493267, 2015). "Certain clinicopathological characteristics of EML4-ALK-positive NSCLCs, including a young age at onset, lack of a smoking history and adenocarcinoma histology, are also observed in patients with NSCLC that harbours EGFR mutations." (PMID 25788996, 2015). "The mean survival time was longer in the group treated with the EGFR inhibitor (17.8 months; range, 8.4–30.1 months) than that in the group without the EGFR inhibitor (10.8 months; range, 0.6–54.0 months) among 52 patients with adenocarcinoma metastases." (PMID 25452785, 2015). "Patients had been diagnosed with either postoperative recurrence or metastatic NSCLC which were all adenocarcinoma, and all patients had ALK fusion gene-positive NSCLC without epidermal growth factor receptor mutations." (PMID 26819719, 2015). "In our study 18 PPLs were adenocarcinomas; in eight cases there was enough material to conduct EGFR analysis and in 10 cases we unfortunately did not obtain enough material." (PMID 26689214, 2015). "One adenocarcinoma was wild type for KRAS, EGFR and EML4-ALK genomic alterations." (PMID 25360587, 2014).